RNU6-322P (RNA, U6 small nuclear 322, pseudogene)
Gene: Small nuclear RNA gene on chromosome 15 (100,551,820 to 100,551,922, reverse strand). Ensembl gene ENSG00000251819.
Homologues: Orthologues: chimpanzee U6 (99% identical), macaque U6 (92% identical), macaque U6 (89% identical), dog U6 (82% identical), pig U6 (79% identical), rat U6 (78% identical), guinea pig U6 (77% identical). Paralogues in human: RNU6-146P (93% identical), RNU6-941P (93% identical), RNU6-1303P (85% identical), RNU6-1060P (84% identical), RNU6-792P (84% identical), RNU6-949P (84% identical), RNU6-166P (83% identical), RNU6-266P (83% identical), RNU6-26P (83% identical), RNU6-338P (83% identical), RNU6-41P (83% identical), RNU6-1011P (83% identical), and 1287 more.